CX3CR1 (C-X3-C motif chemokine receptor 1)
Diseases named in the same sentence as CX3CR1 in open-access papers (continued):
Sharing a sentence is not in itself a finding about the gene and the disease.
melanoma (continued). "Following vaccination against a melanoma-specific epitope, most tumour-specific CD8+ T cells are maintained in a stem-like state, but a proportion of cells lost TRM status and differentiate into CX3CR1+ effector CD8+ T cells in the TDLN, which are subsequently migrating into the tumours." (PMID 36229613, 2022). "Importantly, CX3CR1 expression in human melanoma-infiltrating CD8+ T cells was inversely correlated with the expression of PDCD1, TIGIT, and HAVCR2, which is consistent with our previous flow cytometric analyses of mouse melanoma-specific CD8+ T cells and human melanoma CD8+ TILs." (PMID 38881188, 2024).
myocardial infarction (20 papers, 2013 to 2025). Gross necrosis of the myocardium, as a result of interruption of the blood supply to the area, as in coronary thrombosis. "The Ly6Clo, CX3CR1+ monocyte subset has been associated with wound repair and better functional outcome in models of spinal cord injury, myocardial infarction, and excitotoxic brain injury." (PMID 25469644, 2014). "The genotyping analysis of the subjects enrolled in the present study demonstrated for the first time a direct correlation between CX3CR1 V249I and T280M polymorphisms and the occurrence of acute fatal myocardial infarction." (PMID 24307998, 2013). "We further evaluate if the CX3CR1 polymorphisms could influence the outcome of acute myocardial infarction." (PMID 24307998, 2013). "Thus downregulated CX3CR1 by WXKL may inhibit inflammatory response after myocardial infarction and reduce restenosis risk." (PMID 27843475, 2016). "Here we review the cellular biology of fractalkine and its receptor, along with ongoing studies that introduce CX3CR1 as a future target in coronary artery disease, specifically in patients with myocardial infarction." (PMID 37510939, 2023). "Based on the reports that the Ly6Clo, CX3CR1+ monocytes aid in repair after spinal cord injury and myocardial infarction after 7 days, we expected the monocytes to increase in numbers in the perihematomal brain during the second week after ICH." (PMID 25469644, 2014). "Additionally, the therapeutic potential of targeting this axis is being substantiated in clinical settings, such as the FRACTAL trial, which is evaluating the CX3CR1 antagonist KAND567 in patients with myocardial infarction." (PMID 40508161, 2025). "As myocardial infarction has been implicated to be one of the main causes of heart failure, and one of the independent factors contributing to this is myocardial ischaemia/reperfusion (I/R) injury, the role played by FKN/CX3CR1 has also been assessed." (PMID 37510939, 2023). "Except for CX3CR1−/− mice, which presented with massive diastolic dilatation, we did not observe other differences in ventricular dimensions in other groups four weeks after myocardial infarction." (PMID 36498897, 2022). "At this purpose, we examined the of CX3CR1 polymorphisms presence in individuals who died of noncardiac causes, in a cohort of patients that survived at acute myocardial infarction (AMI survivors) compared with patients died of AMI." (PMID 24307998, 2013). "Also, it was showed that the CD14+CD16+CX3CR1+monocytes might have a role in-stent restenosis following coronary implantation of bare-metal stents in patients with acute myocardial infarction." (PMID 27277665, 2016). "Nine months after bare metal stent implantation after acute myocardial infarction, the number of CD14 + CD16 + CX3CR1 + monocytes in patients with restenosis was higher than that in patients without restenosis." (PMID 39820843, 2025). "Besides, acetate, butyrate, and propionate repaired the myocardial infarction (MI) impairment by reducing the infiltration of CX3CR1+ monocytes to the peri-infarct zone after MI and played an important part in maintaining host immune composition." (PMID 36140990, 2022). "We investigated the association among CX3CR1 genotype, theinflammatory infiltrate subpopulations recruited in the plaque, and the in situ expression offractalkine and its receptor, in patients who died of myocardial infarction (AMI) compared withsubjects who died of noncardiac causes." (PMID 24307998, 2013). "The existence of FFAR2+ and FFAR3+ cells in human myocardial infarction tissue, by immunofluorescent co-staining for FFAR2/3 and canonical marker genes of monocytes and macrophages (CD14, CX3CR1, and CD68), indicating the existence of FFAR2/3 positive monocytes and macrophages." (PMID 40308581, 2025). "Interestingly, IL-35 inhibition reduces cardiac recovery by decreasing monocyte/macrophage survival and the expressions of CX3CR1 and TGF-β after a myocardial infarction in mice." (PMID 37445745, 2023).
myocardial infarction (continued). "It is a selective, non-competitive, allosteric antagonist of the receptor CX3CR1, which had been developed primarily to target inflammation in/during myocardial infarction and other cardiovascular conditions with an inflammatory component." (PMID 37510939, 2023). "We performed myocardial infarction in CCR1−/− (reduced neutrophils recruitment) mice, CCR2−/− (reduced inflammatory monocyte recruitment) mice, CCR5−/− (reduced T-cell recruitment) mice and CX3CR1−/− mice (reduced reparatory monocyte recruitment) mice." (PMID 36498897, 2022). "Moreover, it was reported that patients with restenosis presented a higher count of CD14+CD16+CX3CR1+ monocytes than patients without restenosis after 9 months of the implantation of the bare-metal stent as a result of acute myocardial infarction." (PMID 36741809, 2022).
age-related macular degeneration (18 papers, 2010 to 2025). Age-related loss of vision in the central portion of the retina (macula), secondary to retinal degeneration. "Recent GWAS studies that have implicated CX3CR1-V249I (rs3732349), a putative loss-of-function variant previously associated with age-related macular degeneration, in worsened NFT pathology and Braak staging in AD, and neurodegeneration in ALS." (PMID 35764973, 2022). "Polymorphisms in CX3CR1 have been attributed to a number of inflammatory diseases, including age-related macular degeneration (AMD) and MS." (PMID 34408629, 2021). "There were previous reports that linked the association of polymorphisms in the CX3CR1 and coronary artery disease, risk of acute rejection in renal transplant recipients, cancer rates in renal transplant recipient, age-related macular degeneration, and HIV." (PMID 33986961, 2021). "Third, a genetic variant with reduced levels of CX3CR1 has been associated with the age-related macular degeneration in humans." (PMID 26089772, 2015). "This issue is of particular relevance given the controversial observations linking a polymorphism in the CX3CR1 gene in humans with susceptibility to age-related macular degeneration." (PMID 26514658, 2015). "Third, a genetic variant with reduced levels of CX3CR1 has been associated with age-related macular degeneration in humans." (PMID 26089772, 2015). "Many other reports found an association of polymorphisms in CX3CR1 and other diseases such as coronary artery disease, risk of acute rejection in renal transplant recipients, cancer rates in renal transplant recipients, age-related macular degeneration, and HIV." (PMID 40733585, 2025). "Interestingly, our previous results from an unrelated neurodegenerative condition, age-related macular degeneration, suggested that deletion of the chemokine receptor CX3CR1 led to deleterious actions of the CCL2-CCR2 axis." (PMID 28320442, 2017). "Interestingly, based upon our own previous results from age-related macular degeneration, we found evidence suggesting that this involves microglial CX3CR1 signaling." (PMID 28320442, 2017). "Apart from AD, CX3CL1/CX3CR1 is also involved in other neuroinflammation disorders, including Parkinson's Disease (PD), multiple sclerosis (MS), tauopathies, and age-related macular degeneration (ARMD)." (PMID 27429982, 2016). "The chemokine receptors CX3CR1 and CCR2 have been implicated in the development of age-related macular degeneration (AMD)." (PMID 25503251, 2014). "Cardinal features of age-related macular degeneration were shown to be elicited by subretinal microglia cell accumulation, and this is CX3C chemokine receptor 1 (CX3CR1)-dependent." (PMID 37240109, 2023).
depression (18 papers, 2010 to 2025). "PPAR-γ/CX3CR1/Nrf2 is implicated in depression which the key signaling mechanism of oxidative stress." (PMID 40308754, 2025). "The fact that CX3CR1 loss reduces social interactions with WT mice is consistent with reports showing disrupted CX3CL1-CX3CR1 signaling is associated with schizophrenia and depression-two diseases characterized by social withdrawal/isolation." (PMID 34887755, 2021). "Based on our finding of CX3CL1 and others, further study should assess the interactions between CX3CL1 on neurons and CX3CR1 on microglia to reveal communication mechanisms of microglial regulation in neuroinflammation-associated depression." (PMID 30135647, 2018). "The present study also shows novel data that the loss of CX3CR1 was associated with pronounced social withdrawal and extended depression-like behavior after an acute injection of LPS." (PMID 21167054, 2010). "Heart failure comorbid with depression may be associated with five hub genes, including Stat4, Cd83, Cx3cr1, Col1a2, and Sh2d1b." (PMID 39295096, 2024). "CX3CR1 levels were found downregulated in schizophrenia and may be associated with a depression-anxiety phenotype." (PMID 36993785, 2023). "To summarise, the present study further supports that LPS-activated inflammasomes accelerate neuroinflammation and lead to depression by triggering PPARγ/CX3CR1/Nrf2 and the NF-κB/NLRP3 signaling pathways." (PMID 40308754, 2025). "DD rats had obvious depressive symptoms, which were alleviated after CX3CR1 antibody intervention, suggesting that the depression behaviors were affected by CX3CR1-related pathways in DD rats." (PMID 36072409, 2022). "It has been found that the fractalkine (FKN)/CX3CR1 signaling pathway regulates the transmission of information between hippocampal neurons, triggering a proinflammatory response and inducing depression." (PMID 36072409, 2022). "Here we show that CX3CR1-/- mice exhibited prolonged social withdrawal and depression-like behavior after LPS injection." (PMID 21167054, 2010). "CX3CR1-/- mice or control heterozygote mice (CX3CR1+/-) were injected with LPS (0.5 mg/kg i.p.)or saline and behavior (i.e., sickness and depression-like behavior), microglial activation, and markers of tryptophan metabolism were determined." (PMID 21167054, 2010). "More importantly, the present study discovered that KF1 could reverse the pathological changes in the LPS-induced depression model by activating PPAR-γ/CX3CR1/Nrf2 signaling, and suppressing NF-κB/NLRP3 signaling pathways." (PMID 40308754, 2025). "For example, chronic mild stress (CMS) could decrease CX3CR1 levels in the hippocampus, and this change was associated with CMS-mediated microglial activation and depression-related behaviors." (PMID 34683104, 2021). "Interestingly, microglia were found to be hyper-ramified in a chronic despair mouse model of depression, and this morphological change was mediated by neuron-microglia signaling via CX3CR1, and restored by antidepressant treatment." (PMID 32917850, 2020). "Interestingly, upregulation of CX3CR1 and non-inflammatory microglia were found in post-mortem brain tissue of patients with the major depressive disorder, suggesting that the roles of CX3CR1 and microglia-mediated inflammation in depression need to be further investigated." (PMID 35610721, 2022). "Therefore, we hypothesized that the increased depression-like behaviors in CX3CR1-/- mice would be coupled with exaggerated turnover of TRP, along with changes in monoamine turnover." (PMID 21167054, 2010). "The protein levels of CX3CR1 and Arginase1 (Arg1), which were related to stress vulnerability and depression in our previous studies, were not changed in the hippocampus." (PMID 37396924, 2023).
depression (continued). "Prenatal stress seems to affect the fractalkine axis diversely since in an animal model of depression based on the prenatal stress procedure, the hippocampal and cortical levels of CX3CL1 and CX3CR1 are diminished and return to normal values during therapy with antidepressants." (PMID 33498837, 2021).
ovarian carcinoma (18 papers, 2013 to 2026). A malignant neoplasm originating from the surface ovarian epithelium. "Barbolina and colleagues were able to demonstrate that downregulation of CX3CR1 leads to reduced peritoneal metastasis, and increased receptor expression in human ovarian cancer was associated with a worsened prognosis." (PMID 39862711, 2025). "The TISIDB database assessed that CX3CR1 gene expression was significantly associated with immunoinhibitors in epithelial ovarian cancer, including HAVCR2 (R = 0.51, P < 2.2e−16) and CSF1R (R = 0.66, P < 2.2e−16)." (PMID 38241595, 2024). "Those various online databases reflected CX3CR1 was strongly associated with immunological properties in the epithelial ovarian cancer niche." (PMID 38241595, 2024). "Due to CX3CR1 gene elevated expressed in epithelial ovarian cancer, the mutation map of CX3CR1 gene in epithelial ovarian cancer through the cBioPortal database was observed, including mutation, amplification, deep deletion, and multiple alterations." (PMID 38241595, 2024). "Totally, 422 epithelial ovarian cancer cases included, results showed higher expression of CX3CR1 (above median) was associated with a significant shorter OS (HR = 1.4, P = .012), but no different for DFS (HR = 1, P = .920)." (PMID 38241595, 2024). "We examined a total of 22 genotypes of CX3CL1 and CX3CR1 to explore the association between different genotypes and the clinical efficacy of carboplatin treatment in ovarian cancer patients." (PMID 36685881, 2022). "Association of CX3CL1 and CX3CR1 SNPs with the clinical efficacy of carboplatin treatment in ovarian cancer patients." (PMID 36685881, 2022). "Genotypes and allele frequency of CX3CL1/CX3CR1 SNPs in carboplatin-treated ovarian cancer patients (n = 127)." (PMID 36685881, 2022). "In a follow-up study, we will add more toxicity indicators of chemotherapy drugs to comprehensively evaluate the effect of CX3CL1/CX3CR1 gene polymorphisms on the clinical efficacy of carboplatin in patients with ovarian cancer." (PMID 36685881, 2022). "Furthermore, TIMER database visualized various forms of CX3CR1 copy number and immune cells immersion in epithelial ovarian cancer, showed that CX3CR1 arm-level depletion was associated with the infiltration of macrophages." (PMID 38241595, 2024). "Expanding on these previous studies, we hypothesized that the loss of CX3CR1 may render ovarian carcinoma cells vulnerable to PARPis as well." (PMID 39594684, 2024). "In this study, we selected ovarian cancer patients who were treated in our hospital from January to December 2020 to conduct relevant clinical trials to explore the clinical efficacy of CX3CL1/CX3CR1 gene polymorphisms in carboplatin-treated patients." (PMID 36685881, 2022). "As research continues to advance, the role of the CX3CL1/CX3CR1 biological axis in tumors is gradually being explored, but the roles of their gene polymorphisms in ovarian cancer are relatively unknown and require more exploration." (PMID 36685881, 2022). "Furthermore, high CX3CR1 expression in ovarian cancer was associated with an unfavorable prognosis." (PMID 38241595, 2024). "Therefore, in this study, we used Sequenom Mass ARRAY technology to perform high-throughput analysis of CX3CL1 and CX3CR1 gene polymorphisms, aiming to explore the effect of CX3CL1 and CX3CR1 gene polymorphisms on the clinical efficacy of carboplatin in the treatment of ovarian cancer." (PMID 36685881, 2022). "Interestingly, CX3CR1 overexpression has been associated to worse overall and reduced progression-free survival of platinum-, gemcitabine-, and topotecan-treated ovarian cancer patients, highlighting a prospective therapeutic strategy to restore sensitization by targeting CX3CR1." (PMID 33810010, 2021). "An intraperitoneal syngeneic ovarian cancer model was established by injecting ID8 cells into wild-type and Cx3cr1-deficient mice." (PMID 42279436, 2026).